PDCD1 (programmed cell death 1)
Diseases named in the same sentence as PDCD1 in open-access papers (continued):
Sharing a sentence is not in itself a finding about the gene and the disease.
tumor (continued). "Overall, consistent with the findings from our in vitro experiments, the results from in vivo xenograft models confirmed that the engineering of T cells to secrete IL-12 from the PDCD1 locus can profoundly enhance the anti-tumor activity of NY-ESO-1-specific TCR-T cells." (PMID 36793716, 2023). "Owing to weak co-stimulation and tumor microenvironment signaling, TGFβI may reduce Satb1 induction, thereby increasing PDCD1 levels and further locking T-cell in a depleted state." (PMID 37091977, 2023). "Ginseng polysaccharides achieve anti-tumor effects by altering the gut microbiota and kynurenine/tryptophan ratio, enhancing anti-programmed cell death 1/programmed cell death ligand 1 (anti-PD-1/PD-L1), targeting GPX4, and facilitating macrophage and NK cell activation." (PMID 37571224, 2023). "Also, critical immune checkpoint genes such as LAG3, PDCD1LG2, CD274, IDO1, PDCD1, and CTLA4 were evaluated because these genes are activated when T cells identify and attach to associated proteins on other cells, such as certain tumor cells." (PMID 37876438, 2023). "Recent progress in understanding tumor–immune dynamics emphasizes ICIs targeting cytotoxic T-lymphocyte-associated protein 4 (CTLA-4) and programmed cell death protein 1 (PDCD1, also known as PD-1), which enhance therapeutic outcomes across several malignancies." (PMID 38003674, 2023). "CD8+ TEXs expressing CST7 instead of CTLA4 or PDCD1 was detected in tumour tissues." (PMID 36855810, 2023). "I-E TIMEs are densely packed with immune cells but devoid of cytotoxic lymphocytes (CTLs) in the tumor core, whereas I-I TIMEs are densely packed with CTLs expressing programmed cell death 1 (PD-1), and leukocytes and tumor cells within I-I TIMEs express immune-dampening PD-1 ligand (PD-L1)." (PMID 37511228, 2023). "Furthermore, studies have shown that programmed cell death ligand 1 (PDL1) on sEVs is a pool that directly interacts with programmed cell death 1 on cells to promote tumor growth and mediate immune evasion in GBM, which affects the outcome of immunotherapy." (PMID 36853330, 2023). "Therefore, Labarriére and colleagues edited PDCD1 melanoma-specific T cells and monitored their anti-tumor activity upon adoptive transfer in immunodeficient mice." (PMID 37347257, 2023). "In this work, we examined the relationship between immune cells and tumor immune infiltration, and we found that immune inhibitory receptors such as PDCD1, CTLA4, TIM3, and LAG3 may be important for T cell activation in tumor cells." (PMID 38248311, 2023). "Hyperglycemia impairs immune response; however, it remains unknown whether the anti-tumor effects of anti-programmed cell death-1 antibody (PD-1-Ab) treatment are changed in hyperglycemic conditions." (PMID 37046033, 2023). "In patients suffering from HCC, it has been shown that the expression of PDCD-1 on CD8+ T cells is constantly increased, and tumor evasion and a poor prognosis for HCC were associated with a high frequency of circulating and tumor-infiltrating PDCD-1+ CD8+ T cells." (PMID 37131179, 2023). "The blockade of the programmed cell death 1 (PD-1) or of its ligand (PD-L1) may activate T cell stimulatory signaling, thereby enhancing antitumor T cell cytotoxicity and promoting tumor destruction." (PMID 37760441, 2023). "As a consequence, upregulation of IDO1 expression in tumor cells, programmed cell death 1 (PD-1) in CD8+ T cells and forkhead box P3 (FOXP3) in CD4+ T cells occur, overall impairing CD8+ T cells proliferation and promoting the conversion of CD4+ T cells to Tregs." (PMID 37122718, 2023). "Moreover, our analysis of the TCGA datasets also revealed a significant positive correlation between NFATC2 and PDCD1 across six distinct tumor types." (PMID 37833788, 2023).
tumor (continued). "It has been found that high lactate levels inhibit T cell functions, including interleukin-2 secretion and T cell receptor activation, while blocking lactate dehydrogenase A in tumor cells improves immune function and the efficacy of anti-programmed cell death 1 therapy." (PMID 38139250, 2023). "PDCD1 is mainly expressed by CD4+ and CD8+ T lymphocytes, whereas its ligand, CD274, is widely expressed in various cell types including activated lymphocytes, fibroblasts, tumor-associated macrophages and tumor cells." (PMID 36979400, 2023). "PDCD1 regulates T-cell activity by binding to CD274 or PD-L2 on the surface of tumor cells." (PMID 36979400, 2023). "Additionally, CBX2 and CEP55 had a significantly greater impact on tumor patient survival than PDCD1 and CD274." (PMID 37980163, 2023). "Monoclonal antibodies against immune checkpoint blockade molecules—such as CTLA-4 (cytotoxic T lymphocyte antigen 4), PD-1 (programmed cell death 1), and PD-L1 (programmed cell death ligand 1)—target the tumor microenvironment (TME) with an obvious objective response rate for KIRC." (PMID 36759775, 2023). "To edit the PDCD1 locus of tumor-specific TCR-T cells that recognize the cancer testis antigen, NY-ESO-1157–165 SLLMWITQV (NY-ESO-1 TCR-T cells), we first transduced T cells with lentivirus encoding NY-ESO-1 TCR and then subsequently conducted Cas9 RNP/AAV6 knock-in into transduced T cells." (PMID 36793716, 2023). "Programmed cell death ligand-1 (PD-L1) is an immune checkpoint (IC) expressed on various tumor cells, and its binding to its receptor Programmed cell death 1 (PD-1), which is expressed in various immune cells, including tumor-infiltrating T cells, results in immune evasion." (PMID 38203458, 2023). "Furthermore, KLRB1 expression levels are significantly correlated with tumor purity, immune infiltration, and immunotherapy-related markers such as PDCD1, CD274, and CTLA4." (PMID 37988189, 2023). "Furthermore, scRNA-seq analysis revealed that CD47 was substantially expressed in tumor cells, and we discovered that riskscore were positively linked with CD47, PDCD1, TIGIT, and LAG3." (PMID 37021054, 2023). "PDCD1 takes TAM as a direct target to inhibit tumor progression." (PMID 35186730, 2022). "Furthermore, we found that CSF-1R was significantly correlated with tumor-related immunosuppressive molecules (including PDCD1, CTLA4, CD80, CD86, HAVCR2)." (PMID 35444953, 2022). "In addition, programmed cell death 1 (PD-1) and PD-ligand 1 (PD-L1) play an important role in tumor immune evasion by blocking the activation of cytotoxic T cells." (PMID 36106025, 2022). "Immunotherapies, such as programmed cell death-1 or programmed cell death-ligand 1 inhibitors, also demonstrate encouraging clinical benefits including response rate, and the immune checkpoint represent a useful target to enhance tumor regression." (PMID 36439518, 2022). "Among ICIs, the representative (PDCD1,PD-1) inhibitor, its (CD274,PD-L1) inhibitor, and cytotoxic T-lymphocyte associated protein 4 (CTLA4) restore the ability of immune cells to fight tumors by counteracting the inhibition of the immune system by tumor cells." (PMID 35600371, 2022). "These hub genes showed remarkably associated with immune checkpoints (CD274, PDCD1 and CTLA4), which suggested that these hub genes may play an important role in tumor immune escape in HCC patients." (PMID 35637248, 2022). "Programmed cell death-1 (PD-1) receptors are up-regulated on activated T cells and interact with programmed cell death ligand 1 (PD-L1) on the surface of tumor cells and immune cells to produce immunosuppression to weaken the body's anti-tumor effect." (PMID 35260954, 2022). "Programmed cell death ligand 1 (PD-L1) on tumor cells or tumor derived exosomes binds programmed cell death 1 (PD-1) on T cells and efficiently stimulates cytotoxic CD8+T cell malfunctioning and apoptosis, allowing cancer cells to escape from the immune attack." (PMID 34983557, 2022).
tumor (continued). "To further investigate the relationship between KIRP tumor immunity, we performed the correlation analysis between KIRP immune checkpoint genes (CTLA4, HAVCR2, PDCD1, PDCD1LG2, and TIGIT) and high mutation frequency genes (TTN, MET, KMT2C, PKHD1, SETD2, and KMT2D)." (PMID 36618928, 2022). "There are some existing reviews that refer to targeted protein degradation (TPD) strategies for tumor immunotherapy, but they merely focus on molecule designs and their applications in programmed cell death 1 (PD-1)/programmed death ligand 1 (PD-L1) immune checkpoint." (PMID 36080223, 2022). "As an example, transforming growth factor-β1 (TGF-β1) increases the expression of the programmed cell death-1 (PD-1) receptor by enhancing antigen-driven PD-1 gene transcription through Smad3 transcriptional activation in T cells in vitro and in tumor-infiltrating lymphocytes in vivo." (PMID 35432324, 2022). "In addition, since FREM2 mutation was associated with immune infiltration, we analyzed its association with the expression levels of PDCD1, CD274, CTLA4, LAG3, TIGIT, and HAVCR2, which are important immune checkpoints responsible for tumor immune escape." (PMID 35252356, 2022). "In terms of PDCD1, the expression was positively associated with TOP2A expression in 12 tumor types, including BRCA, HNSC, HNSC-HPV−, HNSC-HPV+, KIRC, LGG, LIHC, LUAD, LUSC, PRAD, THCA (Rho = 0.191) and THYM, but a negative relationship in UCEC (all p values < 0.05)." (PMID 35778520, 2022). "However, programmed cell death-ligand 1 (PD-L1) on the surface of tumor cells binds to the activated CD8+ T cell receptor programmed cell death-1 (PD-1), which significantly inhibits the ability of CD8+ T cells to kill tumor cells." (PMID 35299748, 2022). "Interestingly, we also observed a parabolic expression in genes involved in immune exhaustion (e.g. TCF7, LAG3, CTLA4 and PDCD1), which is consistent with the peak of immune landscape remodelling at S2 tumours as shown by our data above." (PMID 35301339, 2022). "H2BC9 and H2BC11 positively correlate with the immune checkpoint PDCD1, which mediates inhibitory pathways that are exploited by tumors to mitigate antitumor immunity and escape destruction by the immune system, thereby promoting tumor survival." (PMID 36387186, 2022). "Immunotherapy is one of the most important breakthroughs in cancer treatment, and, compared with standard therapies, immune checkpoint inhibitors targeting programmed cell death 1 (PD-1) have been found to significantly prolong overall survival (OS) in patients with many different tumor types." (PMID 35797413, 2022). "A low tumor mutation load, lack of tumor antigen and T-cell homing chemokine, and the immunosuppressive expression of programmed cell death 1 (PD-1)/PD-L1 will lead to immune tolerance." (PMID 36605217, 2022). "Because we observed a paucity of PDCD1 transcript in the CD62L+ tumor infiltrating NK cells, we believe that PD-1 surface expression on these NK cells could be because of trogocytosis." (PMID 36185379, 2022). "The single-cell profiling of T-cell repertoires across a number of gliomas identified an NK-cell like subset of cytotoxic T cells marked by CD161 with increased PDCD1 activity and the impaired killing of tumour cells, highlighting the bidirectional interplay between tumour and immune cells." (PMID 36230865, 2022). "The anti-tumor function of T cells in TME may be suppressed by the FOXP3+ regulatory T cells (Treg) activity or by the PD-1 (programmed cell death 1)/PD-L1 (PD-1 ligand) interactions." (PMID 36359314, 2022). "A study showed that tumor-infiltrating CD8+ cytotoxic T-cells in AML had upregulated inhibitory receptors such as programmed cell death 1 (PD-1), cytotoxic T-lymphocyte antigen 4 (CTLA-4), T-cell immunoglobulin and mucin domain-containing protein 3 (TIM-3), and lymphocyte-activation gene 3 (LAG3)." (PMID 35601490, 2022).
tumor (continued). "Moreover, p5091 was reported to significantly modulate the phenotype and function of M2 (CD11b+F4/80+CD86−CD206+) macrophages, and combinational treatment of p5091 and Programmed Cell Death 1 (PD1) antibody exerted synergistic anti-tumor effect in lung cancer." (PMID 35307036, 2022). "Hence, we analyzed the relationships between the signature and TIP-related genes, and the results showed that cold tumor genes such as CXCL2 and CCL20 and hot tumor genes such as CXCR3, CXCL11, and PDCD1 were upregulated in the high-risk group in both cohorts." (PMID 35938001, 2022). "Second, the TCGA database may include screening for genes that indirectly affect tumor prognosis, such as PDCD1." (PMID 35646101, 2022). "Programmed cell death-1 (PD-1) is a transmembrane glycoprotein expressed in activated T cells, and programmed cell death ligand 1 (PD-L1) is expressed on antigen-presenting cells and tumor cells." (PMID 35911673, 2022). "Mast cells could regulate inhibitory immune response to stimulate tumor immune activity and maintain the balance of the tumor microenvironment similar to the function of programmed cell death 1 (PD-1) and programmed cell death ligand 1 (PD-L1)." (PMID 36313179, 2022). "However, anti-PD-L1 treatment resulted in upregulation or downregulation of numerous genes in CD45+ tumor-infiltrating immune cells in TCh3 tumors, including Cd3d, Cd3e, Cd3g, Cd8a, Cd8b1, Nkg7, Ccl5, Ets1, Icos, Cxcr6, Pdcd1, Lag3, Prf1, and Gzmb (right)." (PMID 35366939, 2022). "The positive correlation of the risk score with the expression levels of PDL1 (CD274), PDCD1, and CTLA4 was found, suggesting that metabolic reprogramming genes may have a significant effect on the tumor immune microenvironment." (PMID 33413205, 2021). "Indeed, we found that Tox and Tox2 directly control the transcriptional regulation of Pdcd1 and Lag3 expression, largely determining the functional incompetence of tumor-infiltrating CD4+ T cells from CD4/ALK4-KO mice." (PMID 34548096, 2021). "Despite the expansion of PD-1 checkpoint blockade to multiple types of cancer, whether the programmed cell death 1 (PD-1) expression status on CD8+ tumour infiltrating lymphocytes (TILs) could be a prognostic factor in cervical cancer is still unclear." (PMID 34150643, 2021). "PD-L1 interacts with the programmed cell death 1 (PD-1) receptor on T cells to induce T-cell exhaustion, and the monoclonal antibody therapy blocks this inhibitory interaction to re-activate T-cell-mediated tumor killing." (PMID 34832863, 2021). "The programmed cell death-1 (PD-1)/programmed death-ligand 1 (PD-L1) pathway regulates T-cell activation and function and controls the induction and maintenance of cell-based immune tolerance within the tumor microenvironment." (PMID 34572736, 2021). "Moreover, CDCA7 was significantly correlated with tumor-related immunosuppressive molecules including PDCD1, CD274, CTLA4, BTLA and LAG3." (PMID 33648519, 2021). "Higher objective response rates to PDCD1/CD274 monotherapy have been associated with a number of factors, including immunogenicity of the tumor, male sex, age < 65 years, current and former smokers, a lack of central nervous system or liver metastasis, and a lack of EGFR mutations." (PMID 34067485, 2021). "Equally important is that T cells have immune checkpoint-dependent immunosuppression, e.g., programmed cell death 1 (PD-1) receptor expressed on T cells binds to its two ligands, PD-1 ligand 1 (PD-L1) and ligand 2 (PD-L2), which are upregulated on tumour cells." (PMID 34795289, 2021). "Until now, the research in this field is mostly carried out at the tumor tissue level, whether methylation statuses of PDCD-1 and LAG-3 in PBL could be involved in the anomalous expression of ICs and related to CRC risk remain unclear." (PMID 34544358, 2021).
tumor (continued). "Mainly, drug targets in PAs are based on general features of tumor cells such as immune checkpoints, so that programmed cell death 1 (ligand 1) (PD-1/PD-L1) targeting may bear potential to cure aggressive PAs." (PMID 35011868, 2021). "Lastly, we examined the frequency of somatic copy number alterations (SCNA) associated with regulation of anti-tumor immune responses in pre-clinical and clinical studies: gains in MYC16, losses of PTEN17 and gains or losses in interferon pathway genes (PDCD1, STAT1, JAK1, and JAK2)." (PMID 34446728, 2021). "Moreover, PDCD1 expression was increased in ILC2s obtained from tumor tissues compared with ILC2s obtained from NSCLC PBMCs." (PMID 34194433, 2021). "Kynurenine metastasis of tumor cells can upregulate programmed cell death-1 (PD-1) in T cells." (PMID 34616452, 2021). "They hamper the tumor immune escape by blocking key immunosuppressive molecules such as programmed cell death 1 (PD-1) and its ligand (PD-L1) and releasing the “brake” of cytotoxic T cells to eliminate tumor cells, however, response rates of ICIs remain limited." (PMID 34039409, 2021). "PD-1 (programmed cell death-1) inhibitors such as nivolumab and pembrolizumab have been shown to have promising anti-tumor activity in the second-line treatment of HCC and have been approved by the FDA for HCC patients, who were previously treated with sorafenib." (PMID 34327136, 2021). "In this sense, metronomic paclitaxel combined with programmed cell death 1 (PD-1) mAb in a syngeneic breast cancer mouse model improved the anti-tumor efficacy of the immune checkpoint inhibitor as monotherapy, with a significant benefit in survival and reduced toxicity." (PMID 34771577, 2021). "Multiple probes in PDCD1 were hypomethylated in the tumor, more so in MSS." (PMID 34638440, 2021). "The immune checkpoint molecule, programmed cell death 1 (PD-1), is expressed by activated T cells and regulates immune responses by binding its ligand, programmed cell death ligand 1 (PD-L1), which can be expressed by tumour cells." (PMID 34676050, 2021). "PD-L1 molecule (PD-L1) plays an important role in mediating immune responses and tumor tolerance by binding to programmed cell death 1 (PD-1) on T lymphocytes and subsequently promoting T cell exhaustion, apoptosis, and the selective suppression of tumor-specific T cells." (PMID 34195077, 2021). "Programed cell death ligand-1 (PD-L1), secreted by tumor cells, combined with programmed cell death-1 (PD-1) located on the surface of activated T-cell, macrophages, etc., in the tumor microenvironment, promotes immune tolerance sustaining tumor immune escape, growth, and progression." (PMID 34572782, 2021). "To predict the sensitivity to ICIs between low- and high-risk groups as classified by the GDPLichi model, we further examined immunotherapy-related markers such as tumor mutation burden (TMB), neoantigen, and expression of PDCD1 (PD-1), CD274 (PD-L1), and CTLA4." (PMID 34970479, 2021). "We investigated the combination of an anti-programmed cell death 1 (aPD-1) monoclonal antibody with the knockdown of vascular endothelial factor receptor 2 (VEGFR2) on tumor endothelial cells to overcome resistance to immune checkpoint inhibitors and improve the objective response rate." (PMID 33291555, 2020). "Studies have found that programmed cell death-1 (PD-1) on tumor-infiltrating lymphocytes (TILS) can be combined with the programmed death ligand-1 (PD-L1) on tumor cells and then inhibits T cell proliferation and activation, thus inducing immune escape of tumor cells." (PMID 32884946, 2020). "T cells, including tumor-infiltrating lymphocytes, were successfully gene edited using the three specific endonucleases (SENs), as well as the BEs described earlier, to target programmed cell death-1 (PD-1)." (PMID 33117361, 2020).